BRCA1 (BRCA1 DNA repair associated)
Diseases named in the same sentence as BRCA1 in open-access papers (continued):
Sharing a sentence is not in itself a finding about the gene and the disease.
tumor (continued). "However, there are also some caveats concerning cf- and evDNA profiling; e.g., cfDNA comprises circulating free tumor-derived (ct)DNA and non-tumor-derived DNA, released from other somatic cells in the body, which can also be mutated (BRCA1 variants)." (PMID 35205822, 2022). "Using a highly multiplex immunofluorescence and image analysis we generate spatial proteomic data for 21 markers in 124,623 single cells from 112 tumor cores originating from 31 tumors with BRCA1/2 mutation (BRCA1/2mut), and from 13 tumors without alterations in HR genes." (PMID 35149709, 2022). "First, the expressions of BRCA1 and -2 genes in a tumor can be suppressed by hypermethylation of the gene promoter, or somatic mutations and large chromosomal rearrangements can be found in these genes, although the impact of these changes on PARP inhibitors and platinum sensitivity remains unclear." (PMID 36613648, 2022). "While the studies presented here suggest improved responsiveness of BRCA1/2-associated GCs to platinum-based intervention, other DNA damaging agents such as PARP inhibitors (PARPi) may also prove useful as PARPi have shown selective killing of BRCA1/2 mutant tumor cells." (PMID 36497436, 2022). "No further BRCA1/2 somatic inactivating variant was identified in tumor samples by NGS." (PMID 35039532, 2022). "Both approaches and further analysis demonstrate that BRCA1 negatively regulates S100A9 in mammary epithelium and the activated S100A9-CXCL12 signaling upon BRCA1 deficiency acts as a driving signaling to establish the tumor microenvironment, which renders tumor cells insensitive to ICB." (PMID 35304461, 2022). "However, a comprehensive view of the tumor microenvironment (TME) and the interplay of tumor, immune and stromal cells of BRCA1/2 mutated tumors has not yet been described." (PMID 35149709, 2022). "We first assessed TDP type 1 status, which is a collective term that comprises all three BRCA1-linked TDP variations, including TDP group 1, TDP group 1/2 mix and TDP group 1/3 mix, as a genomic forensic tool to ascertain critical exposure to BRCA1-specific deficiency during tumor development." (PMID 35857626, 2022). "However, when the HspBP1-overexpressing version of each cell line was injected into mice, both BRCA1-proficient cell lines led to markedly lower tumor outgrowth and size than the control, whereas the BRCA1-deficient cells did not." (PMID 35387978, 2022). "We aimed to identify whether PFS or OS may be associated with factors such as age, sex, smoking status, histopathology, tumor stage, combined with anti-angiogenic therapy status, TKI-targeted therapy before chemotherapy status, HR gene mutation, BRCA1/2 mutation, and driver gene mutation status." (PMID 36591485, 2022). "Additional practice changes, including BRCA1 and BRCA2 mutation testing by gynecologic oncologists and reflex tumor testing by the Department of Pathology, may also be evaluated in future years to determine their impact on detecting BRCA1/2 positivity (i.e., rates)." (PMID 36547149, 2022). "Therefore, we hypothesized that elevated S100A9 levels in BRCA1-MT mammary epithelial tissue might progressively direct immunosuppressive milieu formation and promote tumor initiation and progression in mammary tissues." (PMID 35304461, 2022). "Among the 760 tumor samples successfully sequenced, 178 (23.4%) cases harbored a pathogenic/likely pathogenic (P/LP) mutation, 74 (9.7%) cases showed a variant of uncertain significance (VUS) only, and 508 (66.8%) were defined as BRCA1 and BRCA2 wild type (wt)." (PMID 35406410, 2022). "No carriers of the tumour BRCA1 and/or BRCA2 mutations were identified in the patient group." (PMID 34444865, 2021). "It has to be underlined that both on blood and on tumor tissue BRCA1/2 testing should be cautionary performed, considering that about 10% of PDAC have a genetic cause and a genetic counselling is mandatory to correctly treat all the BRCA1/2 germline mutation carriers." (PMID 34200245, 2021).
tumor (continued). "In this scenario, negative germline reports may advise a tumor study for the determination of somatic variants and the possibility to perform BRCA1/2 testing on tumor tissues would allow us to detect both germline and somatic alterations." (PMID 34200245, 2021). "Thus, in tumors with BRCA1 aberrations, the sum of mitotic defects may result in mitotic catastrophe, increased tumor cell death/better therapeutic response and improved survival." (PMID 33482905, 2021). "Together, regulation of BRCA1 expression and functions in both epithelial and nonepithelial cells within the tumor microenvironment may be important for BRCA1-associated tumorigenesis and invasiveness." (PMID 35008272, 2021). "Thus, tumor suppressors and proapoptotic molecules like BRCA1 or PTEN bind to IP3R to boost Ca2+ ion uptake at MAMs while tumor promoters and anti-apoptotic molecules such as Bcl2 or Bcl-xL repress mitochondrial Ca2+ ion overload by binding to and inhibiting the channel activity." (PMID 34572262, 2021). "The average level of mRNA expression of BECN1 and BRCA1 in the 240 tumors with shallow deletion CNV was lower than the corresponding level in the 50 tumors with diploid CNV, indicating that the monoallelic loss of the tumor suppressor gene reflected in lower mRNA expression." (PMID 33670664, 2021). "Moreover, the exosome-treated BRCA1-deficient fibroblast was shown to acquire a more CAF-like phenotype, with increased proliferation, migration, and invasion ability and this was related to enhanced tumour cells growth in vivo." (PMID 34283046, 2021). "Moreover, O6BG abolished CDDP-activated RAD51 and p-BRCA1 expression in tumor specimens." (PMID 33397362, 2021). "In this context, BRCA1/2 testing on tumor tissues could be combined with other biomarker evaluations, thus saving time and biological materials and allowing us to identify a higher number of patients eligible for available targeted therapies or to be enrolled in ongoing clinical trials." (PMID 34200245, 2021). "There is a high interpersonal variability in the modality and timing of tumor onset in BRCA-mutated subjects, thus suggesting a potential role of other genetics, epigenetics, or environmental individual risk factors in modulating the penetrance of BRCA1/2 germline mutations." (PMID 34552867, 2021). "Rucaparib was also approved by the FDA for patients with deleterious BRCA1 or BRCA2 mutation (germline and/or somatic)‐associated mCRPC who have been treated with androgen receptor‐directed therapy and a taxane‐based chemotherapy based on the tumour testing findings of the TRITON2 study." (PMID 33630412, 2021). "Importantly, mutations in the BRCT domain of BARD1 did not lead to an increased tumour formation in mice, unlike BRCA1 BRCT mutations." (PMID 33755171, 2021). "Although a portion of each tumor subtype contain known cell signaling defects in a single pathway, such as the BRCA1 pathway, it is not feasible to identify, test, develop, and produce a rAAV vector targeting each individual component of the mutant BRCA1 signaling cascade." (PMID 34201599, 2021). "Interestingly, estrogen activated EMT in BRCA1-deficient, but not in BRCA1-proficient tumor cells, independent of ER." (PMID 33540843, 2021). "In particular, on the basis of the pre-clinical evidence that CX-5461 triggered synthetic lethality in tumor cells deficient for BRCA and resistant to PARP inhibitors, the compound has entered phase I clinical trials in 2016 for patients with solid tumors characterized by BRCA1/2 aberrations." (PMID 34073075, 2021). "Thus, R-loop-targeting drugs, possibly in combination with a telomerase inhibitor, might represent interesting approaches to BRCA1-mutant tumor therapy." (PMID 34112789, 2021). "Importantly, our in vivo results show that tumor-bearing mice harboring the same Brca1 mutation (Brca1-Δ11) were not uniform in their responses to irradiation." (PMID 33767581, 2021).
tumor (continued). "Also, increased levels of bioavailable oestrogens in early adulthood (associated with insulin levels and decreased sex hormone binding globulin) could induce earlier differentiation of mammary cells and expression of the BRCA1 tumour suppressor gene." (PMID 34072619, 2021). "At the ASCO 2020 symposium, a study investigating the role of olaparib in women with HER2-negative breast cancer and a germline alteration in DDR pathway, such as PALB2, CHEK2, and ATM, or a somatic tumor mutation without a germline BRCA1/2 mutation was presented." (PMID 34900718, 2021). "BRCA1 methylated tumours are also sensitive to PARP inhibition, as are tumours with mutations in other genes that function in repair of double strand breaks (DSBs), including RAD51C, RAD51D, ATM and PALB2, where tumours are described as having a “BRCAness” phenotype." (PMID 34445211, 2021). "Sequencing-based tests such as the BRCA1/2 classifier and HRDetect/CHORD determine the total mutation load acquired over the course of tumor evolution, implying that resistance due to prior treatment with DNA double strand break-inducing agents might not show up in these sequencing-based tests." (PMID 33670893, 2021). "Although few data are available, the analysis of ctDNA could provide several advantages in clinical practice of PDAC and it should be useful also for the evaluation of BRCA1/2 gene mutations, particularly when tumor tissue is not available or adequate." (PMID 34200245, 2021). "Several predictive and prognostic markers, such as age, menopausal status, tumor grade, the value of Ki-67 proliferative index, presence of tumor-infiltrating lymphocytes (TILs), BRCA1/2 status, and programmed death-ligand 1 (PDL1) expression, could be used in clinical practice." (PMID 33808149, 2021). "Due to growth and differentiation defects induced by Brca1 and Gata3 deficiency 15, 19, 29-32, mice deficient for either Brca1 or Gata3 rarely develop tumors, making it difficult to identify the role of Brca1 and Gata3 loss in regulating EMT in tumor development and metastasis." (PMID 34373738, 2021). "We also demonstrated that C-C chemokine motif ligand 5 (CCL5) is responsible for maintaining CAF activation, and neutralizing CCL5 could attenuate PARPi-induced CAF activation in vitro and in both BRCA1/2-wild type and BRCA1/2-mutant xenograft models and boost the tumor inhibitory effect of PARPis." (PMID 34108603, 2021). "The BRCA1 mRNA-low group also had a higher percentage of large (T4) tumors, but the majority of patients in both the BRCA1 mRNA-low and -high groups still fell into large tumor size (T3/T4) categories, making it difficult to make conclusions regarding tumor size." (PMID 34611475, 2021). "This might reveal tumor microenvironment contributions to drug response and acquired genetic alterations in the presence or absence of BRCA1 loss." (PMID 34944915, 2021). "As a whole, these data suggest that loss of Brca1 induces EMT and metastatic basal-like tumors in an epithelium-autonomous manner and that Brca1 loss activates Pdgfrβ-Pkcα signaling in epithelial tumor cells thereby enriching the number of tumor cells with EMT-like features." (PMID 33478572, 2021). "Importantly, only three out of fifteen patients with deleterious DDR alterations harbored tumor mutations in BRCA1 or BRCA2 and no information is provided on the responses of these three patients." (PMID 34067105, 2021). "For tumours with no pathogenic variant, BRCA1 promotor hypermethylation status should be determined as it is unclear whether this would lead to expression profiles that mimic those associated with pathogenic variants." (PMID 33081408, 2020).
tumor (continued). "We found that the expression of PTEN and BRCA1 was increased after silencing circIQCH, indicating that circIQCH might also decrease the expression of these two important tumor suppressors by inducing promoter hypermethylation through circIQCH- miR-145-DNMT3A axis." (PMID 32756009, 2020). "No carriers of tumor BRCA1 and or BRCA2 mutation were identified in the patient group." (PMID 33374116, 2020). "Indeed, almost half of the women who had undergone clinical BRCA1/2 sequencing without findings of pathogenic germline variants had a tumor with BRCA1 hypermethylation." (PMID 32719340, 2020). "In depth, the c.143T>A variant, dropping in the BRCA1 RING domain, a very conserved region with a function as E3 ubiquitin ligase, could be speculated as affecting the ubiquitination process which is essential for tumor suppressor function of BRCA1 protein." (PMID 32438681, 2020). "Furthermore, African American patients show a higher mutation frequency of BRCA1 (10.2%) and BRCA2 (5.7%) tumor suppressor genes comparing to European non-Ashkenazi Jews White patients (BRCA1: 6.9%, BRCA2: 5.2%)." (PMID 32873298, 2020). "In the four HR gene mutation cases, three of them (PDX1, PDX2, PDX3) exhibited statistically significant decrease in tumor burden when treated with Olaparib (P < 0.05 for all cases) and unsurprisingly all harbored BRCA1/2 mutation while the PDX4 who carried LIG1 mutation did not respond to Olaparib." (PMID 32005272, 2020). "However, BRCA1 functions differently as compared to DAPK1; BRCA1 is a tumor suppressor." (PMID 32328088, 2020). "Furthermore, the xenograft mouse model supports our hypothesis that NU1074 plus SU11274 displays a significant reduction of tumour growth in a cell line with low levels of BRCA1/2 and c‐MET." (PMID 32686903, 2020). "Therefore, BRCA1 may control DNA replication and S phase progression in response to DNA damage, two hallmarks of its tumor suppressor activity, through at least in part positive regulation of DBF4B translation." (PMID 32290274, 2020). "However, the remarkable restriction of BRCA1-related tumours to large hormone-responsive tissues begs the questionon whether the tumour suppressor role of BRCA1 is connected to a hormone homeostasis throughout the breast and ovaries." (PMID 34803264, 2020). "Therefore, understanding the epigenetic mechanisms that control the methylation of proteins responsible for DNA repair after IR (including BRCA1) could be important to design therapies that avoid the resistance of tumor cells to radiotherapy." (PMID 32764667, 2020). "Furthermore, BRCA1 protein level was decreased in bone marrow tumor, while NSD2 level was elevated." (PMID 32826945, 2020). "Very recently, molecular insights have emerged about the role of FANCS (BRCA1) in regulating the mitophagy process; FANCS, indeed, inhibits ataxia-telangiectasia mutated (ATM)-AMP-activated protein kinase (AMPK)-DRP1-mediated mitochondrial fission and promotes tumor proliferation and invasion." (PMID 32962238, 2020). "The only misclassified tumour using the BRCA1 classifier had BRCA1 promoter hypermethylation and reduced BRCA1 expression, suggesting tumours without a pathogenic variant may display a “BRCA-like” phenotype." (PMID 33081408, 2020). "Furthermore, PEG3 mutation was significantly associated with high TMB and inferior prognosis, and the associations were independent of multiple confounding factors including age, tumor stage and mutations of BRCA1, BRCA2 and POLE." (PMID 32729618, 2020). "Since BRCA1/BRCA2 tumor testing can detect simultaneously both somatic and germline variants, with the exception of some variants like rearrangements, a higher number of patients who may benefit from PARPi can be identified at a faster turnaround time and at a lower cost." (PMID 32850417, 2020). "Therefore, positively controlling CCNL2 translation may represent a novel mechanism through which BRCA1 exerts its tumor suppressive activity." (PMID 32290274, 2020).
tumor (continued). "BRCA1 hypermethylation confers an HRD, immune cell type, genome-wide DNA methylation, and transcriptional phenotype similar to TNBC tumors with BRCA1-inactivating variants, and it can be observed in matched peripheral blood of patients with tumor hypermethylation." (PMID 32719340, 2020). "Especially in germline testing of patients, who have a verified somatic pathogenic BRCA1/2 mutation in tumor tissue, or with no family history of HBOC but personal history suggestive of genetic predisposition, methods capable of identifying low-level mosaicism should be used." (PMID 32468491, 2020). "Moreover, as recently reported by Janice Kwon, tumor BRCA testing may represent a cost-effective method of triaging women with EOC for genetic counseling and a confirmatory germline test to identify BRCA1/2 mutations carriers." (PMID 31653094, 2019). "None of the familial BRCA1/2 mutations were found in the tumor samples tested." (PMID 31346352, 2019). "Thus, we hypothesized that the role of the PALB2 linker protein may be critical for BRCA1/2-mediated tumor suppression." (PMID 31877165, 2019). "BRCA1 has also been found to play an important role in chromatin remodeling and gene transcription, indicating that BRCA1 may have pleiotropic functions during tumor development." (PMID 31273285, 2019). "However, it has to be mentioned that, in another study, the missense substitution p.Ile26Ala, abrogating E2 binding and thus ubiquitin-ligase activity, was found to prevent tumor formation to the same degree as wild-type Brca1 in three conditional genetic models." (PMID 30696104, 2019). "In the present study, we demonstrated for the first time that BRCA1 formed a co‐repressor complex with ZBRK1 on the promoter of GOT2 via the ZBRK1 recognition element, and that BRCA1 deficiency promoted aspartate and α‐KG production and accelerated tumor cell growth along with GOT2 upregulation." (PMID 30714292, 2019). "Interestingly, it has been shown that BRCA1 transcription is strongly repressed under hypoxic conditions, suggesting that inadequate BRCA1 expression and functions can be found in the hypoxic tumor microenvironment in solid tumors." (PMID 31273285, 2019). "Thus, patient stratification based on BRCA1/2 status may help identify those tumours vulnerable to chlorambucil." (PMID 31273933, 2019). "We found that both BRCA1 and BRCA2-mutated tumors had significantly more indels (Wilcoxon test, p = 1.6 × 10− 5 for BRCA1 and p = 1.4 × 10− 3 for BRCA2) and structural variants (Wilcoxon test, p = 5.1 × 10− 7 for BRCA1 and p = 0.029 for BRCA2) per tumor than the sporadic tumors." (PMID 31182087, 2019). "We do not know the exact mechanisms that regulate CTSS-specific BRCA1 degradation, but one possible explanation is pH: CTSS is the only pH-dependent protease and IR affects the pH of the cells, which may affect the tumor microenvironment and activate BRCA1 degradation." (PMID 30006610, 2019). "Hence, to circumvent the embryonic lethality and to study the role of these tumor suppressors in pancreatic development and malignant transformation, we specifically deleted Palb2, Brca1 or Brca2 in the pancreas only using the Cre-LoxP recombination technology." (PMID 31877165, 2019). "However, whether these universally important BRCA1 functions in maintenance of genomic stability are sufficient to account for its tissue-specific tumor-suppressing function remains unclear." (PMID 30558184, 2018).